CD34 (CD34 molecule)
Diseases named in the same sentence as CD34 in open-access papers (continued):
Sharing a sentence is not in itself a finding about the gene and the disease.
leukemia (continued). "In particular, higher BCR/ABL-OOF expression levels were found in most undifferentiated hematopoietic CD34+ cells compared to CD34-cell population and indicate Rac as a new therapeutical target to block in order to inhibit leukemia stem cells." (PMID 26682280, 2015). "Eight genes (BAALC, CD14, CD34, CD74, DNTT, HLA-DRA, IRF8, and MN1) were all associated with “leukemia” (P = 1.15 × 10−4), “acute myeloid leukemia” (P = 9.37 × 10−3), and “proliferation of myeloid cells” (P = 0.044)." (PMID 26517675, 2015). "CD34+ was used for leukemia-initiating cells, and CD44+CD24− or ALDH1+ was used to enrich breast cancer-initiating cells." (PMID 26376676, 2015). "The present study found that the use of an anti-CD82 monoclonal antibody (CD82 mAb) mobilized CD34+ leukemia cells from BM into the peripheral blood in a humanized AML murine model." (PMID 26139471, 2015). "Mechanistically, the sulforaphane and imatinib combined treatment can kill CD34+CD38− leukemia stem cells by inducing ROS production and decreasing the GSH level." (PMID 26273420, 2015). "Since both uPAR and CXCR4 are up-regulated in leukaemias, we focused on miRs endowed with oncosuppressor activity and involved in CD34+ HSCs mobilization and/or expressed in leukaemias." (PMID 26082201, 2015). "AML is typically a stem cell-driven disease, and the existence of leukemia stem cells (LSCs) was first identified (CD34 + CD38-) by JE Dick in 1994; these cells extremely promote AML progression, chemo-resistance and recurrence." (PMID 25890196, 2015). "More recently, several reports have shown that CD34+/CD38+ hematopoietic progenitors are able to acquire the ability to maintain populations of LSC or leukemia-initiating cells (LIC)." (PMID 25369030, 2014). "In leukemia, for instance, stem cells are enriched in the CD34+ fraction and further enriched in the CD34+/CD38− fraction, yet the ‘real’ leukemia-initiating cell is believed to be represented by an even smaller subpopulation of CD34+/CD38− cells." (PMID 25216521, 2014). "Discrimination between putative leukemia stem cells and normal hematopoietic stem cells in this large-scale study allowed to demonstrate the clinical importance of putative CD34+CD38- leukemia stem cells in AML." (PMID 25244440, 2014). "Phospho-STAT6 was significantly increased in all leukemia groups in comparison to the normal CD34+ samples." (PMID 25568664, 2014). "Phospho-STAT1 was significantly decreased in all leukemia groups as compared to normal CD34+ samples." (PMID 25568664, 2014). "A short course of high-dose methylprednisolone therapy was reported to increase CD34 (+) progenitor cells and shorten chemotherapy-induced neutropenia in children with leukemia." (PMID 25541649, 2014). "CDKI-73 was more potent than the pan-cdk inhibitor flavopiridol and showed >200-fold selectivity against primary leukemia cells when compared with normal CD34+ cells." (PMID 24495868, 2014). "The goal of the current study is to investigate the effect of nilotinib on drug retention in leukemia-initiating CD34+CD38− stem cells and characterize the interactions of nilotinib with ABC transporters in primary leukemic blasts." (PMID 24651611, 2014). "This putative normal HSC, CD34+CD38– ALDHbright, cell population of 7 of these 19 CD34-positive AML cases was essentially devoid of cells with the leukemia-specific cytogenetic abnormalities FLT3-ITD and/or mutated NPM1." (PMID 24244383, 2013). "Activation of the p38 MAPK pathway contributes critically to the erythroid differentiation of leukemia cell lines induced by various agents and of primary CD34+ hematopoietic progenitors induced by EPO." (PMID 23483889, 2013). "The percentage of leukemia initiating cells (FISH+CD34+CD38-) was then quantified as the value of the percentage of FISH-positive cells multiplies the percentage of CD34+CD38-cells in the blast (CD45dimSSClow)." (PMID 24517186, 2013).
leukemia (continued). "Discrimination and purification of CD34+CD38– LSC and CD34+CD38– HSC have been performed by using leukemia-associated proteins identified by us and others." (PMID 24244383, 2013). "In our previous experiments, we had shown that phenotypically diverse ALL blasts, mainly characterized by expression of CD19 and CD34, are able to propagate the human leukaemia in immunodeficient mice." (PMID 23229821, 2013). "KG-1a cells are a type of short-term CD34+ hematopoietic progenitor cell line, and contain leukemia stem-like cells characterized by the CD34+CD38− biomaker; in some cases, the leukemic stem-like cells comprise about 50% of the total KG-1a cells." (PMID 23698050, 2013). "Compared to normal PBMC and CD34+ cells (overall RARβ2 methylation levels 2%), the leukemia cell lines analyzed had variable degrees of DNA methylation, which was highest (59%) in HL-60, followed by Kasumi-1 and SKNO-1 (34% and 36%, respectively)." (PMID 24116031, 2013). "In acute myeloid leukemia (AML), the leukemia initiating cells (LICs) or leukemia stem cells (LSCs) is found within the CD34+CD38- cell compartment." (PMID 24517186, 2013). "The same study identified several upregulated miRNAs predicted to target CD34, a gene whose expression is frequently downmodulated in these leukemias." (PMID 24278756, 2012). "Initially, it was thought that the LSC resided in the CD34+CD38- compartment, but many anti-CD38 antibodies, including those utilized in the original isolation of LSCs inhibit engraftment of CD34+CD38+ leukemia cells through an Fc-dependent mechanism." (PMID 22876360, 2012). "CD34+/c-Kit+/P-glycoprotein+/MRP1+ TF1 leukaemia progenitor cells have been reported to be unusually resistant against PCD." (PMID 23071514, 2012). "In order to provide more information about the potential antileukemic action of violacein, in the present study we examined the effect of violacein on a chemoresistant CD34+/c-Kit+/P-glycoprotein+/MRP1+ TF1 leukaemia progenitor cell line." (PMID 23071514, 2012). "Tertiary transplant experiments revealed that the human CD45+CD34+CD2+CD7+ population propagated leukemia and seeded hematopoietic niches, which was demonstrative of LIC self-renewal capacity." (PMID 22768113, 2012). "We isolated stem/progenitor-enriched CD34+ cells from bone marrow and blood cells in lymphoma and leukemia patients, as well as in normal donors." (PMID 23028717, 2012). "The findings from the murine model were then extended to human leukemias, using primary CD34+/CD19+ cells purified from peripheral blood of patients with Ph+ or Ph− B-ALL." (PMID 22564882, 2012). "We found that latexin was down-regulated in a variety of leukemia and lymphoma cell lines as well as in CD34+ cells from the blood and marrow of patients with these malignancies." (PMID 23028717, 2012). "CD34+CD38- leukaemia cells are largely quiescent and reported to be resistant to chemotherapeutic drugs." (PMID 23013471, 2012). "Using the polony results, we compared the total levels of wild type and alternatively spliced transcripts in the leukemia samples, which revealed that c-myb alternative splicing was dramatically increased in the leukemias compared to normal CD34+ cells." (PMID 21853052, 2011). "In conclusion, our study demonstrates that BALB/c Rag2-/-γc-/- mice transplanted with human CD34+ cord blood cells provides an in vivo model to define the early steps of HTLV-1 infection that might lead to a better understanding of the initiation of the HTLV-1 associated leukemia." (PMID 21909275, 2011). "With this identification it was determined that only cells that were located in the CD34+/CD38- population of progenitor cells had the capacity to initiate leukemia in NOD-SCID mice when compared with CD34- and CD34+/CD38+ cells." (PMID 21439058, 2011).
leukemia (continued). "Here, by performing a detailed, single molecule assay we found that c-myb alternative RNA splicing was elevated and much more complex in leukemia samples than in cell lines or CD34+ hematopoietic progenitor cells from normal donors." (PMID 21853052, 2011). "For the L-GMP sample, MLL-AF9 fusion gene was expressed in mice to create the leukemia model and C-kit+, FcR+, CD34+ and Lin- antibodies were used to isolate the Granulocyte Macrophage Progenitor (GMP) cells from the bone marrow." (PMID 22103807, 2011). "Anti-apoptotic Bcl-2 contributes to the survival and chemoresistance of quiescent leukemia CD34+ cells." (PMID 21595920, 2011). "In this study, we enriched CML stem/progenitor cells from 3 patients with CML-BC using CD34 selection kit and successfully isolated CD34+ leukemia cells (the yield: 89.37%±6.79%)." (PMID 21887305, 2011). "By analyzing the levels of expression in leukemias and normal samples we identified three splice variants: Del8, 9A and 9S/10 that were consistently expressed more highly in the leukemias than in the normal CD34+ progenitor cells." (PMID 21853052, 2011). "The anti-apoptotic proteins Bcl-2 and Bcl-xl also contribute to the survival and chemoresistance of quiescent leukemia CD34+ cells." (PMID 21595920, 2011). "We first examined miR-92a expression levels in leukemia cell lines as well as CD34-positive cells obtained from healthy volunteers." (PMID 21182798, 2010). "We found high miR-92a expression in leukemia cell lines as well as in CD34-positive cells obtained from healthy volunteers." (PMID 21182798, 2010). "We reasoned that the initial effects of oncogenes are likely to confer the proliferation advantage that leads to leukemia, and sought to identify those early effects using nucleofection to identify deregulated genes in primary human CD34+ cells within 6 h." (PMID 20805992, 2010). "For example, CD34+CD38- cells in leukemia, CD44+CD24low/lin- cells in breast cancer and CD133+ cells in brain and prostate tumors." (PMID 19744348, 2009). "Other cell cultures, designated LAD 1 and 2, derived from bone marrow aspirates from a patient with mast cell sarcoma/leukemia, resemble CD34+-derived human mast cells with functional FcεRI and Fcγ RI receptors." (PMID 19379488, 2009). "Indeed, the stem cell phenotype induced by FBXO11 depletion is sufficient to cooperate with AML1-ETO and KRASG12D to produce a synthetic serially transplantable leukemia from normal CD34+ cells." (PMID 41289019, 2026). "Additionally, when CD34+ cells from NPM1c samples are transplanted, they can reconstitute a CD34- leukemia, thus suggesting CD34+ cells from NPM1c are leukemia initiating cells." (PMID 40269321, 2025). "Importantly, patients with CD34+CD38- leukemia cells with high ALDH activity manifest a significantly lower complete remission rate, as well as poorer event-free and overall survival." (PMID 40643557, 2025). "Administration of ISO after G-CSF mobilization was found to increase the number of favorable cells—likely to induce graft-versus-leukemia (GvL) effects, such as NK and γδ T cells—while decreasing the number of unfavorable cells—likely to provoke GvHD, such as B cells—per CD34 + cell count." (PMID 41194247, 2025). "In CD34+ haematopoietic cells isolated from both healthy donors and leukaemia patients, researchers observed that cancerous CD34+ cells became stiffer and underwent brittle failure when subjected to external force, whereas healthy CD34+ cells maintained their structural integrity." (PMID 40387441, 2025). "Notably, this effect was leukemia specific with less impact on healthy CD34+ hematopoietic stem and progenitor cells." (PMID 38942785, 2024). "Curcumin showed strong cytotoxicity towards a human leukemic stem cell line (IC50 of 14 microM), and another curcuminoid, bisdemethoxycurcumin, greatly repressed the expression of Wilms’ tumour 1 and CD34 protein, warranting further studies to control leukaemia stem cells." (PMID 38612718, 2024).
leukemia (continued). "Furthermore, cell surface CD74 was identified to be highly expressed in LSCs of AE9a mice and CD34+ human leukemia cells." (PMID 38922758, 2024). "Notably, elevated PRMT9 protein levels were seen in an LSC-enriched (CD34+CD38−) relative to a leukemia committed progenitor (CD34+CD38+) subset or to either of the normal subsets." (PMID 38413714, 2024). "Therefore, identifying CD34+/CD38+/CD19+ self-renewing B-ALL cells introduces a hierarchy of leukemia-initiating cells that differ from AML." (PMID 37692500, 2024). "LMO2 was highly and homogenously expressed across all leukemia populations, but also in monocytes and dendritic cells and the majority of CD34+ cells, even before GT, making it an unreliable transcriptional marker to distinguish the leukemic clone from non-malignant progenitors." (PMID 38688902, 2024). "We sorted the leukemia CD34+ subset and CD34−CD33+ blasts from specimens (n = 7)." (PMID 38413714, 2024). "To determine whether Phf6 deficiency suppresses AML progression by decreasing LSCs (leukemia stem cells) number and activity, we analyzed the frequency and absolute number of c-Kit+ and L-GMP (Lin− c-Kit+ IL-7R− Sca-1− CD16/32+ CD34+) LSCs in BM and spleen." (PMID 38336746, 2024). "While stemness can be defined functionally, stem cell associations are difficult to determine, since the only protein marker that can be consistently viewed as a leukemia stem cell marker is CD34, and this marker also characterizes healthy hematopoietic stem cells." (PMID 37761947, 2023). "They showed that the CD34+/CD38- cell subpopulation from acute myeloid leukemia could form leukemia after transplantation into NOD.SCID mice." (PMID 37284445, 2023). "Finally, BCR::ABL+, BMI1+, and BCR::ABL+/BMI1+ CD34+ cells were transplanted into NOD/SCID mice to test for leukemia induction in vivo." (PMID 38201282, 2023). "Therefore, the precise quantification of CD34+ cells is of the utmost importance for the diagnosis and treatment of leukemia." (PMID 38131753, 2023). "CD34+CD38− lymphoblasts as likely leukemia stem cells (LSCs) may be responsible for a worse response to treatment and may be a risk factor for recurrence in B-cell precursor acute lymphoblastic leukemia (BCP-ALL)." (PMID 37675394, 2023). "The CD34+ cell classification is important for the diagnosis of leukemia for several reasons." (PMID 38131753, 2023). "The first leukemia-initiating cells (LICs) were discovered in the CD34+CD38− section of AML cells." (PMID 37735675, 2023). "Dysregulated proliferation at any stage of hematopoietic cell differentiation can lead to the abnormal accumulation of CD34+ cells in the bone marrow or peripheral blood, making these markers particularly significant for the diagnosis of diseases such as leukemia, characterized by abnormal growth." (PMID 38131753, 2023). "This DL-based approach eliminates the need for separate staining procedures, enabling the rapid and precise detection of CD34+ cells, thereby proving invaluable in leukemia diagnosis, hematopoietic stem cell transplant monitoring, and similar research applications." (PMID 38131753, 2023). "Moreover, CD34+ is a crucial indicator for determining the timing of hematopoietic stem cell collection for leukemia treatment." (PMID 38131753, 2023). "The flexibility of the panel allows it also to be used for leukemia phenotyping through addition of anti-canine CD34 antibody that are labeled by researchers using commercially available antibody conjugation kits with fluorochromes not used in the panel such as PE/Cy5, PE-Texas Red." (PMID 36996049, 2023). "Hence, overexpressing RUNX1::RUNX1T1 in human CD34+ as a single genetic element rather models a pre-leukemic phase of AML allowing for the investigation of additional hits to progress to leukemia." (PMID 38201282, 2023).
leukemia (continued). "Anti-CD117 CAR T cells mediated depletion of leukemic cells and healthy hematopoietic stem cells in NSG mice reconstituted with human leukemia or CD34+ cord blood cells, respectively, and could be terminated in vivo." (PMID 37583386, 2023). "In line with these prior findings, our PPI network analysis showed overrepresentation of genes involved in JAK‐STAT signaling in CD34‐positive leukemias, and further investigation revealed a Ph‐like profile among one‐third of patients with a CD34‐positive LAIP and relapse." (PMID 35271751, 2022). "CD36+CD34+ LSCs have a higher FAO rate compared to differentiated leukaemia cells or normal HSCs." (PMID 35223487, 2022). "In further research, the expression, target genes, and biological function of miR-1246 and miR-224 will be confirmed by more techniques in HQ-induced K562 cells, CD34+ hematopoietic progenitor cells, U937 human leukemia cells, and human peripheral blood mononuclear cells (PBMCs)." (PMID 35366954, 2022). "Notably, we observed that ER stress, which is normally induced by nutrient deprivation or hypoxia, was activated and partially mediated the effects of metformin on CD34+ leukemia cells." (PMID 35444236, 2022). "In the study, although K562 (human chronic myeloid leukemia cell) and Meg01 (human megakaryocyte) cells are considered classical models for studying megakaryocyte differentiation, they are also leukemia cells and differ to some degree from human CD34 hematopoietic progenitor cells that produce PLTs." (PMID 36430539, 2022). "In a tumor transplant experiment in immunodeficient mice, only a small subset of leukemia cells with CD34+/CD38− could regenerate the original leukemia." (PMID 35892847, 2022). "Additionally, in human myeloid malignancies, including AML, chronic myeloid leukemia, and particularly mast cell leukemia, the leukemia-initiating cells are considered to occupy the CD34-positive subpopulation of the malignant clone." (PMID 36072760, 2022). "Here, we show BK124.1 efficacy against the human CML cells in a xenotransplantation mouse model and in the two groups of particularly resistant cells: K562 cells expressing MDR1 (K562-MDR1) and in CD34+/CD38- leukemia stem cells from peripheral blood of CML chronic phase patients." (PMID 35892900, 2022). "Herein, to map changes in protein levels associated with metabolic signature, we integrated label-free quantitative proteomic analysis, transcriptomic data, and metabolic activity assays, aiming to search for CD34+ leukemia cell-specific metabolic vulnerabilities for therapeutic purpose." (PMID 35444236, 2022). "We found CBX2 overexpressed in leukemia both in vitro and ex vivo samples compared to CD34+ cells." (PMID 35681235, 2022). "For instance, it has been reported that THP-1 cells and the CD34 + (KG-1) leukaemia cell line incubated with varying concentrations of rhGM-CSF and rhIL-4 for 5 days showed upregulated levels of CD11c, CD80 and CD86 and of the cell-surface receptors CD40, CD209 (DC-SIGN) but failed to express CD83." (PMID 34800147, 2022). "Accordingly, genes associated with stemness were overrepresented among the most upregulated genes in CD34‐positive leukemias, and protein–protein interaction networks showed an overrepresentation of genes associated with cell migration, cell adhesion, and negative regulation of apoptosis." (PMID 35271751, 2022). "The use of NSG PDX models has also led to a better understanding of the heterogeneity of leukemia-initiating cells (LIC) as reports identified the existence of not only CD34+CD38- LIC cells but also CD34+CD38+ and even CD34- populations capable of initiating AML." (PMID 35756660, 2022). "Another xenograft mouse model to study leukemia has been developed using isolated human CD34+ hematopoietic cells from healthy donors that are transduced with a viral vector expressing system or have been genetically engineered which are then transplanted into immunodeficient mice." (PMID 35756660, 2022).